GALNT8 (polypeptide N-acetylgalactosaminyltransferase 8)
Description:
Probably catalyzes the initial reaction in O-linked oligosaccharide biosynthesis, the transfer of an N-acetyl-D-galactosamine residue to a serine or threonine residue on the protein receptor.
Synonyms: GalNAc-T8
Tractability: Antibody: UniProt predicts a signal peptide or a membrane-spanning region.
Gene: Protein-coding gene on chromosome 12 (4,720,267 to 4,851,927, forward strand). Ensembl gene ENSG00000130035.
Subcellular location: Golgi apparatus membrane
Subcellular location (Human Protein Atlas): Golgi apparatus; Vesicles
Pathways (Reactome):
Metabolism of proteins: O-linked glycosylation of mucins
Gene Ontology:
Molecular function: polypeptide N-acetylgalactosaminyltransferase activity
Biological process: protein O-linked glycosylation; protein O-linked glycosylation via N-acetyl-galactosamine
Cellular component: Golgi apparatus; Golgi membrane
Genetic constraint (gnomAD): Loss-of-function variants: 32 observed, 35.93 expected, observed/expected ratio (o/e) 0.89, 90% interval 0.67 to 1.2. The upper end of that interval is the gene's LOEUF score, 1.2, which puts it in group 5 of 6, group 1 being the genes least tolerant of losing a copy. Missense variants: 497 observed, 503.22 expected, observed/expected ratio (o/e) 0.99, 90% interval 0.92 to 1.06. Synonymous variants: 177 observed, 188.11 expected, observed/expected ratio (o/e) 0.94, 90% interval 0.83 to 1.07.
Homologues: Orthologues: macaque NDUFA9 (92% identical), chimpanzee GALNT8 (88% identical), dog GALNT8 (78% identical), rabbit GALNT8 (76% identical), pig GALNT8 (73% identical), guinea pig GALNT8 (60% identical), zebrafish GALNT8 (48% identical), zebrafish galnt8a.2 (47% identical), zebrafish galnt8b.2 (47% identical), zebrafish galnt8b.1 (46% identical), zebrafish galnt8a.1 (44% identical), Caenorhabditis elegans gly-3 (27% identical), and 3 more. Paralogues in human: GALNT18 (44% identical), GALNT9 (42% identical), GALNT17 (39% identical), GALNT6 (30% identical), GALNT3 (29% identical), GALNT13 (29% identical), GALNT1 (29% identical), GALNT11 (28% identical), GALNT4 (28% identical), GALNT7 (27% identical), GALNT16 (27% identical), GALNT5 (27% identical), and 7 more.
Diseases named in the same sentence as GALNT8 in open-access papers:
GALNT8 is named in the same sentence as 9 diseases in open-access papers, as found by Europe PMC text mining. Sharing a sentence is not in itself a finding about the gene and the disease. The quoted sentences say what the papers report.
breast carcinoma (5 papers, 2022 to 2024). "Supporting this discovery, there was also study reporting that the O-GalNAcylation of BMPR1A by GALNT8 enhanced its activity to transduce BMP signaling in breast cancer." (PMID 38385080, 2024). "In breast cancer, GALNT4, GALNT6, and GALNT8, have been reported to be associated with patient outcomes, whereas no other study examines the clinical role of GALNT1." (PMID 37444599, 2023). "For instance, GALNT8 could suppress the metastasis of breast cancer via suppressing the EGFR signaling pathway." (PMID 38385080, 2024). "EGFR O-glycosylation in breast cancer was impacted by GALNT8." (PMID 36058918, 2022). "GALNT8‐mediated O‐Gal N Acylation suppresses the EGFR signaling pathway and metastatic potential in breast cancer cells." (PMID 38522013, 2024).
retinoblastoma (4 papers, 2020 to 2025). A malignant tumor that originates in the nuclear layer of the retina. "LncRNA GAU1 overexpression in retinoblastoma cisactivates the expression of its target gene GALNT8 to induce retinoblastoma tumorigenesis." (PMID 32366932, 2020). "According to the previous report that GAU1 and GALNT8 share a cisregulation relationship in retinoblastoma and the mutual promoter region of the two genes, investigation on the mechanism behind the abnormal promoter activation in CRC should be conducted in our future studies." (PMID 34239555, 2021). "Our previous study has demonstrated lncRNA GAU1 could recruit Transcription Elongation Factor A1 (TCEA1) to the promoter of Polypeptide N-Acetylgalactosaminyltransferase 8 (GALNT8), thereby upregulate an oncogene expression and accelerate tumorigenesis of retinoblastoma." (PMID 32669100, 2020).
pancreatic adenocarcinoma (1 paper, 2024). "High expressions of GALNT5 and GALNT10 are positively correlated with pancreatic cancer survival, while expressions of GALNT8 AND GALNT10 are negatively correlated with survival in PAAD (pancreatic adenocarcinoma)." (PMID 39433745, 2024).
pancreatic cancer (1 paper, 2024). "The survival map of the hazard ratio showed that only the expressions of GALNT5, GALNT8, GALNT10, and GALNT16 displayed significant differences in prognosis with pancreatic cancer." (PMID 39433745, 2024).
cancer (5 papers, 2016 to 2023). A tumor composed of atypical neoplastic, often pleomorphic cells that invade other tissues. "The in vitro oxaliplatin drug response data revealed that cancer cells overexpressing GAU1 or GALNT8 are more vulnerable to chemotherapy agents causing replication fork collapse, indicating GAU1/GALNT8 axis as a potential actionable target for the personalized medicine of CRC." (PMID 34239555, 2021). "By integrating the differential expression data from 7,256 curated RNA-Seq libraries in MiTranscriptome and experimental validation, we demonstrated that GAU1, together with its downstream protein GALNT8, is associated with cancer cell proliferation, poor patient survival, and chemotherapy response." (PMID 34239555, 2021). "Silencing of GALNT8 suppresses the cancer cell proliferation and induced resistance against oxaliplatin in CRC cell lines." (PMID 34692502, 2021). "Since the relationship between GALNT8 and cancer is limited, we experimentally manipulated the expression of GALNT8 by lentiviral stable overexpression and siRNA interference." (PMID 34239555, 2021). "Together with the experimental evidence overexpression or silencing GALNT8 mimicked the cancer cell line phenotypic alteration after GAU1 overexpression or knockout." (PMID 34239555, 2021). "Our result showed an oxaliplatin hypersensitivity in cancer cell lines overexpressing GAU1/GALNT8." (PMID 34239555, 2021).
tumor (4 papers, 2021 to 2023). "According to the density of IHC staining, GALNT8 protein expression in tumor tissues was classified as high expression (score ++, score +++) in 26 cases (26/69, 37.68%) and low expression (score +, score +/-, and score -) in 43 cases (43/69, 62.32%)." (PMID 34239555, 2021). "Our previous researches showed that the aberrant open chromatin status at chr12p13.3 induces a novel cheRNA GAU1 and cis activates the expression of oncogene GALNT8 by recruiting the transcription elongation factor TCEA1, which accelerates tumor progression." (PMID 33937246, 2021). "Tumor tissues harbored a significantly increase GALNT8 expression compared to the adjacent nontumorous tissues (Fisher exact P = 3.30 × 10−8)." (PMID 34239555, 2021). "The strong expression correlation between GAU1 and GALNT8 was further validated in our 66 pairs of clinical samples (P < 10−4), with a significant upregulation of GALNT8 expression in the tumor tissues (T) compared with the adjacent nontumorous tissues (N) (P < 10−4)." (PMID 34239555, 2021).
GALNT8 also shares sentences with these, for which no sentence is quoted: colorectal cancer (1 paper); glioma (1); melanoma (1).